LGR5 (leucine rich repeat containing G protein-coupled receptor 5)
Diseases named in the same sentence as LGR5 in open-access papers (continued):
Sharing a sentence is not in itself a finding about the gene and the disease.
tumor (continued). "In this system, they reported a moderate upregulation of classic Wnt pathway targets, such as Lgr5 and Axin2 in the intestine, spheroid changes in organoids, and a tumour response driven predominantly by paracrine Rspo3 signals from a minor sub-population of cells." (PMID 28695896, 2017). "Inoculation with LGR5+ SiHa-LGR5 cells led a significantly shorter tumor-free period; for instance, the shortest tumor-free period following LGR5+ SiHa-LGR5 cell implantation was 5 weeks, compared with the 7-week tumor-free period exhibited by mice inoculated with LGR5– SiHa-AcGFP cells." (PMID 28880275, 2017). "LGR5 protein expression was greatly increased in BCC tumor samples as well as metastasis." (PMID 27049829, 2016). "Since LGR5 has been identified as a stem-cell specific gene in ovarian epithelial cells in mice, this pathway may be restricted to tumor cells with stem-like properties, although the role of LGR5 in human ovarian epithelial cells is unclear." (PMID 27215396, 2016). "Moreover, Lgr5-positive follicle stem cells have been shown to contribute to the formation of papillomavirus-induced tumor in the epidermis." (PMID 27835894, 2016). "Therefore, we examined the effect of n-3 PUFA and polyphenol (curcumin) combination on Lgr5+ stem cells during tumor initiation and progression in the colon compared with an n-6 PUFA-enriched control diet." (PMID 27831561, 2016). "After 42 days, immunohistochemical (IHC) staining of tumour tissues indicated that ZG16 expression was significantly increased in the pLenti-ZG16 stably transfected LGR5+ CRC tumors, while significantly decreased in p-miR-196a stably transfected LGR5- CRC tumours." (PMID 27880730, 2016). "Injecting after the first tumors had occurred and subsequent tracing for 2-3 weeks would reveal whether Lgr5+ stem cells in the tumor were fueling the growth." (PMID 27409834, 2016). "Interestingly, LGR5 is higher expressed in SC derived from primary tumor tissue than from traditional cell lines, hinting to a potential enhanced TIC phenotype in SC derived from primary patient biopsies compared to cell line-derived SC." (PMID 26745821, 2016). "Moreover, the Lgr5+/CXCR4+ cells generated significantly more tumor spheres than CXCR4+/Lgr5- and Lgr5+/CXCR4- cells." (PMID 27835894, 2016). "Moreover, the tumor mass formed by Lgr5+/CXCR4+ cells was significantly greater than tumor mass from the other cell populations." (PMID 27835894, 2016). "We therefore examined LGR5 protein levels in primary NBs using immunoblotting in panel of 26 NBs, and observed higher expression of LGR5 in stage 3 and 4 tumours relative to stage 1 and 2 tumours and normal fetal adrenal." (PMID 26517508, 2015). "Given that SKNSH are reported to spontaneously switch between S and N type cells, further investigation into how Lgr5 may play a potential role in this spontaneous transition may lead to new insights into tumor survival and proliferation." (PMID 26697427, 2015). "Both WT and Gpa33−/− mice exhibited activation of the WNT pathway, shown by elevated β-catenin protein and upregulated expression of the WNT target genes, CD44 and Lgr5, in tumours compared to normal epithelium, consistent with CTNNB (encoding β-catenin) being a known AOM target." (PMID 26035389, 2015). "Another study found leucine-rich repeating-containing G-protein coupled receptor 5 (Lgr5) overexpression to be correlated to lymph node metastasis, tumour stage and response to chemotherapy, also showing a tendency to poorer survival in comparison to patients with low Lgr5 expression." (PMID 26854147, 2015). "Additionally, cancer cells in the invasive front presented stronger LGR5 immunoreactivity than that at tumor center (P < 0.05)." (PMID 26416247, 2015). "Conversely, silencing of LGR5 by shRNA showed impressive effects on reduced cellular migration by scratch assay, suggesting that it may be important in tumor migration and aggressiveness." (PMID 26416247, 2015).
tumor (continued). "Lgr5CreERCatnblox(ex3)/+ and Lgr5CreERCatnblox(ex3)/lox(ex3) mice were induced with a single intraperitoneal injection (IP) injection of tamoxifen and rapidly developed small intesti-nal tumours with similar kinetics to those following Apc deletion in the Lgr5 compartment." (PMID 26240067, 2015). "Instead, drug-induction suggested decrease for ITGB1/CD29c and ALDH1B1, while CD24, CD44, CD166, ALDH1A1 and Lgr5 were unchanged as detected by signals from microarrays with pooled tumor RNA from indomethacin-treated patients versus pooled tumor RNA from control patients." (PMID 25340937, 2014). "The results revealed that LGR5 depletion significantly suppressed tumor growth in nude mice." (PMID 24172981, 2014). "Tumours in the small intestine of animals bearing the Lgr5-GFP-CreERT2 transgene and targeted Apc alleles were mainly detected in the distal third of the small intestine with fewer lesions in the proximal part and very few tumours in between." (PMID 25010414, 2014). "All these data indicated that down-regulated LGR5 may attenuate the tumor initiation and progression of HeLa cells." (PMID 25193857, 2014). "In addition, silencing of LGR5 inhibited cell proliferation, secondary tumor sphere formation and induced cell apoptosis, and G0/G1 phase arrest in vitro by modulating Bcl-2, Bcl-xL and Bax." (PMID 24789370, 2014). "Furthermore, we have demonstrated that CD133 and Lgr5 mRNA transcripts were also upregulated in primary tumor-derived RR cells from patients." (PMID 25380620, 2014). "Accordingly, given that Lgr5+ cells are the cells of origin of Wnt-driven tumors in the murine stomach, the expanded pool of Lgr5+ stem cells might be one of the major factors of IM that contributes to tumor development in the human stomach." (PMID 24340024, 2013). "This is of interest as it may indicate a cancer stem cell niche role for tumor-derived Paneth-like cells, similar to their role in supporting Lgr5+ stem cells in the normal intestinal crypt." (PMID 24069241, 2013). "We speculate that the marked increase in the number of Lgr5+ cells during the process of IM has profound biological significance for tumor initiation in the stomach." (PMID 24340024, 2013). "The LGR5 expression levels were graded according to the percentage of LGR5+ tumor cells." (PMID 24340024, 2013). "On the other hand, for the GA with diffuse LGR5 expression in which the majority of tumor cells expressed ISC markers as well, it remains unclear whether all Lgr5+ cells are tumor stem cells." (PMID 24340024, 2013). "Alternatively, quiescent (Paneth cell precursor) tumour stem cells may provide a source of actively cycling Lgr5+ CSCs whose function is then further supported by more mature Paneth cells." (PMID 24069241, 2013). "Lgr5 has been used to study tumor promoting signals in intestinal stem cells." (PMID 23691015, 2013). "To clarify whether the upregulated expression of ISC markers was related to the LGR5+ tumor cells, we microdissected the tumor glands into upper and lower regions and compared the marker transcript levels in both areas." (PMID 24340024, 2013). "Furthermore, patients with LGR5+ tumour cells had a shorter median survival (28.0±8.6 months) compared with LGR5-negative cancers (54.5±6.3 months)." (PMID 22530031, 2012). "More recent publications, on the other hand, reported that LGR5 may actually function as a tumor suppressor and its expression level is inversely correlated with prognosis." (PMID 22615920, 2012). "Notably the LGR5 expression at the tumour centre and the invasion front correlated with tumour growth and nodal spread." (PMID 22530031, 2012). "In addition to that, our findings now implicate that LGR5+ cells and hence the number of stem cells increases and that the stem cell niche re-allocates during carcinogenesis, i.e. to the luminal surface, tumour centre and invasion front." (PMID 22530031, 2012).
tumor (continued). "Our findings indicate that the assessment of AGR2 and LGR5 in PB might reflect the presence of circulating tumor cells (CTC) and stem cell like CTC in CRC." (PMID 22605983, 2012). "LGR5 as an optional Wnt coreceptor, is assumed to mediate the enhancement of Wnt signals by binding soluble R-spondin proteins, therefore playing a role in tumour growth and metastasis." (PMID 22530031, 2012). "The overall distribution of these LGR5+ tumour cell patches was uneven and inhomogeneous." (PMID 22530031, 2012). "In this study we aimed to fill this gap of information and tested the hypothesis that the cancer stem cell marker LGR5 has prognostic and tumour biological significance." (PMID 22530031, 2012). "This indicated that the biological significance of LGR5+ cancer cells may depend on their spatial distribution within the tumour mass." (PMID 22530031, 2012). "We analysed the subcutaneous tumours for LGR5 expression using immunofluorescence." (PMID 21829496, 2011). "The review highlights that targeting LGR5 is a promising anti-cancer treatment but the functional effect of LGR5 on tumor cells is complex may be dependent on cancer type, tumor microenvironment and cross-talk with other molecules in the LGR5 signaling pathway." (PMID 39821694, 2025). "The functional significance of LGR5 in CRC remains complex, with some studies associating high LGR5 expression with poor prognosis and others linking it to better clinical outcomes, possibly reflecting differences in tumor stage, microenvironment, or methodological approaches." (PMID 41002393, 2025). "However, TBX3 expression only partially overlapped with that of other Wnt target genes such as AXIN2 and LGR5, suggesting varying levels of Wnt activation across tumor types, and mechanisms of uncoupled regulation between TBX3 and other targets depending on the context." (PMID 40343989, 2025). "However, the underlying molecular mechanisms of LGR5-mediated tumor promotion or suppression are not fully understood, and further research is necessary to elucidate its role in maintaining homeostasis and tumor growth." (PMID 41194856, 2025). "Notably, LGR5 expression tends to increase during the adenoma–carcinoma sequence but declines at invasive tumor fronts and in budding cancer cells, suggesting context-dependent regulation during tumor progression and invasion." (PMID 41002393, 2025). "A HCC study reported that LGR5 + cells were able to form compact self-renewing spheres associated with doxorubicin resistance, while LGR5- cells could not form tumor spheroids." (PMID 39821694, 2025). "Moreover, combined quantification of LAPTM4B and LGR5 expression demonstrated superior predictive power for tumor progression compared to individual markers, underscoring the synergistic influence of heterogeneous stem‐like cell populations on patient outcomes." (PMID 40661135, 2025). "Unsurprisingly, sensitivity to α-LGR5 ADC treatment increased proportionally to LGR5-expression indicating the potential for an accessible therapeutic window that can be exploited to eliminate LGR5+ tumour cells while avoiding on-target/off-tumour toxicity to healthy cells." (PMID 40405910, 2025). "Depending on different TMEs, LGR5 may promote metastasis or activate tumor-suppressive pathways." (PMID 39821694, 2025). "However, LGR5+ can interact with TGFβ, suppressing tumor metastasis in early-stage tumors." (PMID 39821694, 2025). "Additionally, targeting LGR5 (+) stem cells in a specific phase of cancer and in combination with tumor microenvironment (TME) combination could be a future hotspot." (PMID 41194856, 2025). "In this context, the main strategies to boost NK-cell function against CRC could rely on the use of mAbs or BiKEs targeting CRC tumor antigens (e.g., EGFR, CEA, HER2, MUC-1 and LGR5) that can directly induce tumor cell death but also simultaneously trigger NK cell cytotoxicity via ADCC." (PMID 40607422, 2025).
tumor (continued). "Importantly, generation or presence of Lgr5 positive cells is necessary to form metastases suggesting that cancer stem cells and their niche formation upon metastases seeding is a prerequisite of metastatic tumor growth." (PMID 38659853, 2024). "Similarly, Lgr5+ cell depletion assays also prove the key role of Lgr5+ cells in tumor metastasis." (PMID 39872442, 2024). "Thus, Lgr5+ CSCs reappear when cancer treatment is discontinued, resulting in rapid tumor regrowth." (PMID 39183418, 2024). "The high LGR5 expression in carcinoma with necrosis may be involved in tumor tissue regeneration." (PMID 38787285, 2024). "Therefore, it is possible that the tumor environment and LGR5 expression interact with each other, which may differ between PTs and metastases." (PMID 38787285, 2024). "Subsequent work established murine Lgr5 as a pre-eminent molecular marker of stem cells in the intestinal epithelia, gastric epithelia, hair follicle, foetal mammary gland, nephrons in the developing kidney the regenerating liver and as tumour initiating cells in the small intestinal epithelia." (PMID 39169164, 2024). "Besides, more CD8+ T cell infiltration, higher CD8+ T cell activity, and lower CD44high Lgr5+ expression in the CD45- Epcam+ tumor cells could be observed in the tumor tissues of the Id1Lyz-KO group." (PMID 37996458, 2023). "Moreover, these LGR5-targeted ADCs can dramatically restrain tumor growth and recurrence in vivo." (PMID 37190019, 2023). "However, the interaction between LGR5+ cells and CAFs in HCC has rarely been explored and we hypothesis that CAF‐related microenvironment will influence the behavior of LGR5 expressing tumor stem cell." (PMID 37578396, 2023). "Hence, the existence of CAFs could promote the growth of tumors and enhance the expression number of LGR5 expressing cells in xenograft murine tumor." (PMID 37578396, 2023). "To clarify whether the previous observed metastasis was promoted by CAFs, we established three individual groups in immunodeficient mice, subcutaneously engrafting isolated LGR5+ tumor cells, LGR5+ cells with CAFs and LGR5+ cells with CAFs with DT administration." (PMID 37578396, 2023). "Taken together, our results suggest that LGR5 may act as a tumor suppressor in HGSC progression." (PMID 35778589, 2022). "Others have identified that a small proportion of DCLK1+ tuft cells are Lgr5+ (stem cell marker) and may act as tumour stem cells during intestinal tumorigenesis, and that DCLK1 expression readily differentiates intestinal tumour stem cells from normal stem cells." (PMID 36263033, 2022). "In addition, depletion of POLR1A in LGR5 high cells prevents tumor formation." (PMID 35673898, 2022). "Interestingly, when the same oncogenic hit was overexpressed in LCs (Krt8-expressing cells) or BCs (Lgr5-expressing cells), the resulting tumors were basal-like, HER2-positive, and luminal B (Krt8-derived tumor), or mainly luminal A and B (Lgr5-derived tumors)." (PMID 35052683, 2021). "In conclusion, the study underscores LGR5 as a particularly useful prognostic biomarker and illustrates the strength of combining biomarkers detecting different subpopulations of cancer cells and/or cells in the tumor microenvironment for predicting recurrence." (PMID 35008827, 2021). "Lgr5 is linked with stemness and renewal but not with tumour progression." (PMID 34680897, 2021). "Directly linking high-fat diet-induced accumulation of bile acids to tumour initiation, excess colonic bile acids have been shown to erode the crypt–villus architecture in mice, perturbing locoregional Wnt-signalling gradients and exposing Lgr5+ ISCs to luminal genotoxins and ensuing transformation." (PMID 33673710, 2021). "Importantly, few LGR5(+) colorectal CSCs could grow a tumor with the same phenotype as that of original cells, and silencing the LGR5 gene could increase the apoptosis of tumor cells." (PMID 33713277, 2021). "Thus, LGR5 lineage ablation impedes organoid and tumor initiation and further growth." (PMID 32327656, 2020).
tumor (continued). "Importantly, LGR5 lineage ablation significantly inhibits organoid initiation and tumor growth." (PMID 32327656, 2020). "Both Lgr5 and Lgr6, together with the other member of the same receptor family, namely Lgr4, are recognized mediators of the Wnt signalling pathway, that is activated in human HF tumours, especially TB, and probably in canine TB as well, as indicated by the presence of numerous positive nuclei." (PMID 32397255, 2020). "Besides that, in the present study we observed statistically significant differences in the levels of mRNA expression of the three selected SC markers in the two tumours, suggesting their (in particular, Lgr5) use as potential markers in the distinction between BCC and TB." (PMID 32397255, 2020). "In addition, several studies have suggested that Lgr5 might be a potential target for anti-tumor therapy in GC and CRC." (PMID 31417548, 2019). "Therefore, in this study, we investigated the role of LGR-5 expression in HCC by comparing tumor and normal tissue specimens from Taiwanese people using immunohistochemistry (IHC) staining to determine if LGR-5 expression was an independent clinical outcome indicator of HCC." (PMID 31126119, 2019). "This could be a way of targeting cellular plasticity and a means of maintaining inhibition of primary tumour growth in already established primary tumours, without the associated tissue toxicity caused by sustained direct targeting of LGR5." (PMID 30792270, 2019). "Furthermore, Lgr5+ CSC-targeted drug delivery system might also become a promising approach for targeted anti-tumor therapy." (PMID 31358061, 2019). "Also, Lgr5, a surface-expressed protein, may become a potential therapeutic target for tumor therapy through antibody-based or drug delivery therapies." (PMID 31358061, 2019). "Thus, Lgr5 enables positive B cell selection and tumor initiation in B cell malignancies." (PMID 31358061, 2019). "The tumor surface could only be evaluated in 81 cases, of which 57 (70.4%) expressed LGR5." (PMID 31827644, 2019). "However, following the cessation of LGR5+ cell ablation, mobilisation of LGR5- cells quickly reinstated tumour growth, which may undermine the clinical translation of CSC-targeted therapies." (PMID 29570681, 2018). "Similarly, terminally differentiated enterocytes or DCLK1+ tuft-cells re-express ISC markers (Lgr5, Ascl2, Rnf43) and acquire tumour-forming capacity following simultaneous stimulation of Wnt and inflammation pathways, which support a ‘top-down’ model of CRC initiation." (PMID 29570681, 2018). "LGR5+ cell ablation in CCOs (through an inducible CRISPR/Cas9 system) resulted in apoptosis and tumour regression; however, the LGR5−KRT20+ fraction of CCOs exhibited proliferation competency and could replenish tumour growth through the regeneration of LGR5 expressing cells." (PMID 29844449, 2018). "Indeed, after a single oncogenic hit, represented by mutation of the tumor suppressor APC, only LGR5+ cells are able to generate an overt cancer, while the same lesion occurring in TA cells is not sufficient to induce neoplasia." (PMID 29853913, 2018). "Conversely Lgr6 and Lrig1 tumours have associated stromal inflammation while Lgr5 tumours do not." (PMID 29807713, 2018). "Moreover, LGR5 is known to bind the Wnt receptor component R-spondin, creating a positive feedback loop between aberrant Wnt signaling and expansion of LGR5+ cell populations and contributing to tumor initiation." (PMID 28757546, 2017). "Notably, Lgr5+ tumor cell depletion did not cause tumor regression, but rather tumor stasis, while treatment discontinuation was followed by rapid tumor re‐growth." (PMID 28559443, 2017). "Finally, the finding that the progeny of LGR5+ tumor cells scales with the total number of epithelial cells fits in well with the hypothesis that CRC growth is the result of the activity of multiple LGR5+ tumor stem cells." (PMID 28468934, 2017). "Thus, it is likely that LGR5+ and LGR5− tumor phenotypes are also plastic." (PMID 28468934, 2017).